MET (MET proto-oncogene, receptor tyrosine kinase)
Diseases named in the same sentence as MET in open-access papers (continued):
Sharing a sentence is not in itself a finding about the gene and the disease.
tumor (continued). "Pharmacological inhibition or siRNA-mediated depletion of c-MET inhibits the growth of ARID1A-deficient CRC cells in vitro and tumor xenografts in vivo." (PMID 40369167, 2025). "To investigate the involvement of ETV1, ERG and MET in pro‐tumour capacities and the effect of their concomitant activity, we assessed migration and invasion using Boyden chamber assays, comparing all cell lines." (PMID 39374163, 2025). "In mouse models, it significantly reduced tumor growth, especially in tumors with high MET and AXL expression." (PMID 41011010, 2025). "Next, we investigated the synthetic lethal effect of c-MET inhibitors in vivo using a tumor xenograft mouse model." (PMID 40369167, 2025). "In summary, we have developed novel tumor-targeting PROTACs that selectively degrade membrane c-MET, which balances the therapeutic efficacy and potential toxicity." (PMID 39744222, 2025). "This review focuses on the role of the MET proto-oncogene in cancer and how alterations in this gene contribute to tumor growth and spread." (PMID 40361420, 2025). "First, the miniaturized production of biparatopic anti-c-MET antibody–drug conjugates served as a proof of concept for their applicability in cytotoxic screenings on tumor cells with different target expression levels." (PMID 38396776, 2024). "This review highlights the interplay between tumor cells and myeloid-derived suppressor cells (MDSCs) that create an immunosuppressive environment while providing targets for c-MET-focused immunotherapy." (PMID 39664377, 2024). "This outcome is particularly noteworthy because MET amplification often indicates an aggressive cancer phenotype, yet tepotinib helped manage tumor progression effectively in this case." (PMID 39598385, 2024). "In conclusion, following the paradigm of precision medicine, the accurate evaluation of the HGF/MET axis function in every patient will allow the selection of the optimal MET-targeting immunotherapy approach to obtain the most powerful anti-tumor response." (PMID 38892318, 2024). "The c-MET signaling pathway has emerged as a crucial player in regulating immune cell composition in the tumor microenvironment, particularly immunosuppressive neutrophils, macrophages, and Treg." (PMID 39664377, 2024). "Cell lines expressing higher levels of the MET gene and protein exhibited enhanced tumor growth, metastasis, migration, and drug resistance." (PMID 39221422, 2024). "The interaction between stromal HGF and MET-expressing cancer cells plays a crucial role in tumor development within the tumor microenvironment (TME)." (PMID 39598385, 2024). "MET is overexpressed in PTC and associated with increased extrathyroidal extension rates, higher tumor stages, more frequent nodal metastases, a higher prevalence of BRAFV600E mutations, and an increased 10-year locoregional recurrence rate." (PMID 38017325, 2024). "METex14 mutation impairs MET protein receptor degradation, leading to the sustained activation of MET signaling, which promotes cell proliferation and tumor growth." (PMID 39449330, 2024). "The METex14 mutations were identified in 221 positive cases (0.6%) out of 38,028 profiled tumors in the largest tumor genomic profiling cohort performed for MET alteration." (PMID 39087020, 2024). "After chemoimmunotherapy, the patient exhibited a MET amplified tumor (mean MET copies 11.2 and MET/CEP7 ratio of 3.6) with MET amplification in approximately 93% of cells and concordant strong, diffuse membranous phospho-MET IHC staining (right)." (PMID 38276867, 2024). "When MET is amplified or overexpressed, cells continuously receive proliferative signals, leading to sustained tumor growth." (PMID 39605750, 2024). "Subsequent whole transcriptome RNA sequencing (RNAseq) analysis of the tumor sample revealed a CLIP2::MET fusion." (PMID 38650040, 2024). "The HGF/MET axis can modulate the immune suppressive tumor microenvironment (TME), acting at different levels." (PMID 38892318, 2024).
tumor (continued). "We found that tumor samples that overexpressed the MET genes (CDH2 and TGF genes) had a decreased survival probability in relation to the overall mean expression of those genes." (PMID 38539520, 2024). "In the context of cancer, the shedding of MET by ADAM10 can affect tumor progression by altering how cells respond to growth factors and their surrounding environment." (PMID 39769452, 2024). "When bound to CD3, c-MET BsAbs attract T cells toward tumor cells with heightened c-MET levels, activating and destroying tumor cells." (PMID 39664377, 2024). "In contrast, MET TKIs, including capmatinib and tepotinib, primarily inhibit the tyrosine kinase activity of MET, effectively blocking downstream signaling pathways involved in tumor growth and survival." (PMID 39449330, 2024). "The growing body of evidence underscores the critical roles of galectins like Gal-7, Gal-4, and Gal-3, as well as c-MET, in tumor growth, metastasis, and malignancy." (PMID 39664377, 2024). "It is feasible that upregulation of EGFR and MET in tumor cells contributed to resistance to pembrolizumab monotherapy." (PMID 38916448, 2024). "Tumor cells showed discrete and overlapping expression of MET, Ecad and MITF and were co-expressed with NGFR in a small subset of tumor cells." (PMID 38386085, 2024). "In mouse models with tumors from cell lines or patient tissues exhibiting c-MET overexpression, robust anti-tumor activity was shown by SHR-A1403." (PMID 39664377, 2024). "These phenomena were less evidently seen in the LUSC model, as there was less abundant co-expression of EGFR and MET in the tumor." (PMID 38916448, 2024). "In multiple tumor types, the activation of MET is a subsequent event that intensifies the malignant characteristics of cells that have already undergone transformation." (PMID 38675409, 2024). "Maraver’s lab recapitulated this acquired molecular resistance mechanism by generating an EGFR/MET transgenic mouse model and showed the addition of MET inhibitors to osimertinib-induced tumor regression." (PMID 39796653, 2024). "used serial circulating tumor (ct)DNA to detect MAPK pathway alterations (SNV or indel in RAS/EGFR/BRAFV600 or MET or ERBB2 amplification) after various therapy lines." (PMID 39080202, 2024). "Numerous MET inhibitors have shown notable efficacy in inhibiting tumor growth in both preclinical and clinical settings." (PMID 38596618, 2024). "Another advantage of targeting MET by CAR immunotherapy is the potential hitting of the very inner roots of the tumor because MET expression is an inherent distinctive trait of cancer stem cells." (PMID 38892318, 2024). "Traditionally, tissue biopsies (e.g., tumor sections) have been the primary source for detecting MET protein expression and gene changes for IHC, FISH, and NGS assays." (PMID 39201787, 2024). "MET-positive tumors were defined by IHC as those where at least 50% of the tumor cells showed weak, moderate, and/or strong staining intensity (MET 1+/2+/3+)." (PMID 38892160, 2024). "Combining c-MET inhibitors with TGF-β pathway antagonists offers a promising approach to enhance anti-tumor immunity." (PMID 39664377, 2024). "Of note, MET-amplified tumors had the highest frequency of high PD-L1 scores out of all tested tumor groups, with most of these tumors being detected as PD-L1 high." (PMID 39664186, 2024). "Overall, significant anti-tumor activity in various preclinical models with high c-MET levels was demonstrated by SHR-A1403, suggesting its potential as a therapeutic option for c-MET-overexpressing cancers." (PMID 39664377, 2024). "MSK-LX29 tumor was derived from the patient with EGFR mutant NSCLC who developed resistance after 3 months of erlotinib treatment with an acquired MET amplification and had the highest TWIST1 expression." (PMID 38485737, 2024). "While there is no recurrent gene amplification that was observed, the following genes were amplified in two tumor samples: MET, SMO, ERBB2, BRAF, EZH2, SRSF2, CUX1, and CEBPA." (PMID 38164123, 2024).
tumor (continued). "Anaplastic lymphoma kinase (ALK) and mesenchymal-epithelial transition factor (c-MET) are pivotal receptor tyrosine kinases involved in tumor proliferation." (PMID 39144632, 2024). "Consequently, HGF expression by tumour cells or by the tumour microenvironment could be an attractive biomarker for predicting MET activation and thus its sensitivity to targeted therapies, even in the context of MET mutation." (PMID 38652103, 2024). "In a case report involving a CCA patient with EHBP1-MET fusion, treatment with the MET inhibitor crizotinib led to a partial tumor response lasting 8 months." (PMID 38730642, 2024). "MET amplification has also been identified as a mediator of resistance in NTRK fusion positive tumor and KRAS G12C mutant subtype of NSCLC." (PMID 38485737, 2024). "It exerts its anti-tumor effects by binding to EGFR and c-MET on the tumor surface, thereby inhibiting the activation of their signaling pathways and binding to extracellular segments to promote receptor-antibody complex degradation." (PMID 38774882, 2024). "Immunohistochemistry revealed that the LC3 and LAMP1 expression increased, but the mTOR and MET expression decreased in IL-32γ-overexpressing mouse tumor tissues." (PMID 39519229, 2024). "Studies indicate c-MET signaling affects macrophage function, promoting tumor support via secretion of factors that enhance tumor proliferation and metastasis." (PMID 39592929, 2024). "Volitinib (Savolitinib) is an ATP-competitive inhibitor that has been clinically evaluated in gastric cancer PDX models and showed high anti-tumor efficacy in bearing-amplified MET-selected individuals." (PMID 38334610, 2024). "MET pathway activation can also occur through the upregulation of MET or HGF secretion signals, resulting in tumor transformation, in addition to gene amplification, mutation, or fusion." (PMID 39201787, 2024). "c-MET-specific HTLs also recognized dendritic cells (DCs) pulsed with c-MET-expressing tumor cell lysates." (PMID 39664377, 2024). "The MET gene is overexpressed in over 75% of HNSCC and has an increased copy number of 13%, associated with tumor progression and tumor dissemination in the early stages." (PMID 38952548, 2024). "Our exploratory findings, particularly the observed enrichment of tumor responses in the RAS wild-type subgroup along with upregulation of MET signaling pathway in responders, likely explain the more favorable outcome seen in the CAMILLA and COSMIC-021 trials." (PMID 38378868, 2024). "The DN30 antibody has demonstrated effectiveness in reducing tumor growth in animal models, particularly in tumors with constitutive MET activation due to gene amplification." (PMID 39598385, 2024). "The tumor was derived from a patient who received erlotinib for 3 months and then developed acquired resistance secondary to an acquired MET amplification." (PMID 38485737, 2024). "Given the success of c-MET inhibitors in tumor immunotherapy, the role of this RTK in neutrophils and tumor immunity should be explored further." (PMID 39638788, 2024). "The results indicate MET, ERBB2, SMAD4, and CCNE1 copy-number status is significantly associated with primary tumor site." (PMID 39062773, 2024). "Although TKI drugs inhibit downstream signaling pathways of driver genes, key signaling pathways within tumor cells can still be persistently activated through bypass routes such as MET gene amplification, EGFR gene amplification, and AXL activation." (PMID 39582541, 2024). "The association between treatment outcomes and tumor c-MET levels was constrained by factors such as low treatment effectiveness, rare occurrence of c-MET overexpression, and a small number of patients involved." (PMID 39458991, 2024). "This TKI first showed efficacy in several case studies on patients harbouring MET exon 14 skipping tumours." (PMID 38652103, 2024).
tumor (continued). "Functionally, the BsAb enhanced interferon (IFN)-γ production by 2-3 folds compared to control IgG, inhibited c-MET pathway activation, significantly reduced tumor cell proliferation, and exhibited dose-dependent cytotoxicity against MKN45 cells." (PMID 39664377, 2024). "BMS-794833 is a potent inhibitor that targets both VEGFR and MET and plays a crucial role in tumor angiogenesis and metastasis." (PMID 38532893, 2024). "Recent studies have shown that the involvement of the HGF/c-MET signaling pathway within the tumor microenvironment (TME) is multifaceted and paradoxical." (PMID 39201787, 2024). "MET exon 14 skipping on the other hand is an intragenic rearrangement of the MET gene resulting in sustained MET activation, ultimately leading to cell proliferation and tumor growth." (PMID 38492039, 2024). "Certain CNVs, such as increased MET gene copies, can enhance tumour growth and metastasis, while CNVs in ARHGAP family genes can lead to abnormal ARHGAP expression, affecting patient outcomes and treatment response." (PMID 39075640, 2024). "HGF and its receptor c‐MET are known to shape the hepatic microenvironment and promote tumor growth in liver tumors." (PMID 39359691, 2024). "In my case, tumor regression will also be followed by visible tumor progression, despite continuous treatment with capmatinib, MET inhibitor." (PMID 38188499, 2024). "Vitamin C lowers reactive oxygen species [ROS] in tumor cells, decreasing the activity of SP transcription factors and thus the SP-dependent expression of MET and EGFR." (PMID 39062731, 2024). "Collectively, HGF/c-MET signaling plays a pivotal role in the formation and maturation of new blood vessels, ultimately facilitating the essential blood supply required for tumor progression and metastasis." (PMID 39201787, 2024). "In conclusion, our findings demonstrated that the MET TKIs savolitinib and capmatinib effectively suppressed the proliferation of MET-amplified human GC cells and inhibited tumor growth." (PMID 38892160, 2024). "In the context of cancer, the MET interactome contributes to tumor progression, metastasis, and therapeutic resistance, making these interactions attractive targets for the development of novel anti-cancer therapies." (PMID 39769452, 2024). "The receptor tyrosine kinase inhibitor, cabozantinib (XL184), upstream of the MET pathway, is used to counteract and impair tumor cell proliferation and angiogenesis, promoting myogenic differentiation." (PMID 38474036, 2024). "In conclusion, inhibition of c-MET can increase the number of tumor-infiltrating T cells, enhance their activity, and improve the efficacy of immunotherapy." (PMID 39201787, 2024). "Activation of wild-type MET contributes to drug resistance, not only due to receptor overexpression but also as a result of paracrine HGF secretion by tumor-associated stromal cells." (PMID 39598385, 2024). "BsAb-5 demonstrated efficacy in inhibiting HGF-mediated tumor development and inducing c-MET degradation, supported by in vitro assays and in vivo xenograft studies." (PMID 39664377, 2024). "MET gene amplification, occurring at a rate of around 4% across various tumor types, arises from polysomy or focal copy number gain." (PMID 38892318, 2024). "c-MET and AXL are associated with tumor progression and a poor prognosis, and previous studies have shown that the activation and increased expression of AXL are critical for the development of resistance to midostaurin and quizartinib." (PMID 38978049, 2024). "Researchers have also noted the important role of MET in acquired resistance to tumor TKI targeting." (PMID 39605750, 2024). "For example, c-Met, the protein product of the MET proto-oncogene, has been demonstrated to promote tumor angiogenesis, growth, and metastasis." (PMID 39724112, 2024).
tumor (continued). "Recent studies have demonstrated the efficacy of MET-targeting PROTACs in reducing tumor growth, highlighting their potential as a novel therapeutic approach in various malignancies, particularly those driven by aberrant MET signaling." (PMID 39598385, 2024). "Most importantly, MET fusions enable tumor cells to abolish their dependency on the ligand HGF and participate in the autophosphorylation of components in oncogenic cellular pathways." (PMID 38195556, 2024). "When combined with MET inhibitors, the aim is to simultaneously block both angiogenesis and MET-driven tumor survival and pro-invasive mechanisms." (PMID 39769452, 2024). "The activation of the tumor cellular–mesenchymal to epithelial transition factor (c-MET) signaling pathway by cancer cells frequently promotes tumor formation, invasive growth, and metastasis." (PMID 39204153, 2024). "Most significantly, WntSI effectively overcame acquired resistance to EGFR‐TKIs resulting from MET amplification in both cell line‐derived and patient‐derived tumor xenograft mouse models, while exhibiting exceptional safety measures." (PMID 38867713, 2024). "Multiple studies have shown that c-MET signaling modulates immune cell composition in the tumor microenvironment, particularly immunosuppressive neutrophils." (PMID 39664377, 2024). "This artificial dimerization promoted enhanced wound healing and invasion, highlighting the functional relevance of the MET-β1 complex in tumor progression." (PMID 39769452, 2024). "The drugs included SCR1481B16, a specific MET inhibitor proven to inhibit MET-driven tumor growth, and Anlotinib." (PMID 39605750, 2024). "We cultured tumor cells from our electroporation model in vitro and analyzed the impact of crizotinib or capmatinib treatment on phosphorylation of MET and downstream effectors." (PMID 38849845, 2024). "Cancer-associated fibroblasts and mesenchymal stromal cells produce hepatocyte growth factor (HGF), activating c-MET signaling in tumor cells and myeloid-derived suppressor cells (MDSC)." (PMID 39664377, 2024). "Extensive research has demonstrated that galectin family members, such as Gal-7, Gal-4, and Gal-3, interact with c-MET signaling pathways to drive tumor growth, metastasis, and malignancy across different cancer types." (PMID 39664377, 2024). "These patterns suggest capmatinib's significant role in curbing tumor activity in advanced NSCLC, especially pronounced in patients with MET exon 14 skipping mutation who are untreated." (PMID 38816668, 2024). "Given the MET gene’s broad involvement in tumor progression and metastasis, it is a pivotal target in cancer therapy, particularly in addressing treatment resistance and enhancing therapeutic outcomes." (PMID 39449330, 2024). "ADCC assays further confirmed the cytotoxic effects of ARGX-111 across multiple human cancer cell lines and patient-derived primary tumor specimens, including cancer stem-like cells expressing c-MET." (PMID 39664377, 2024). "In pancreatic ductal adenocarcinoma [PDAC], pancreatic stellate cells in the tumor microenvironment secrete HGF which activates MET and induces HK2 expression in PDAC cells in a paracrine manner." (PMID 39062731, 2024). "Activation of MET, part of the tyrosine kinase family, promotes tumor cell growth, survival, migration, and invasion through activation of downstream oncogenic pathways in the setting of resistance to EGFR TKIs." (PMID 38276867, 2024). "The positive correlation between MET expression and proliferative activity also suggests a potential significant role played by MET expression in tumor progression." (PMID 38596618, 2024). "There was a low percentage of MET amplified cells (6% of cells) at first progression on osimertinib (left) concordant with the LAT006_2B MET polysomy PDX (MET amplification in 2% of cells) generated from the same patient tumor." (PMID 38276867, 2024).